EGFR (epidermal growth factor receptor)
Diseases named in the same sentence as EGFR in open-access papers (continued):
Sharing a sentence is not in itself a finding about the gene and the disease.
adenocarcinoma (continued). "CSD might predict the approximate PFS and OS time in the patient with EGFR mutation -positive adenocarcinoma through this graph." (PMID 30055587, 2018). "We investigated whether CSD was an independent factor affecting the PFS, OS, and efficacy of EGFR-TKI in patients with EGFR mutation-positive adenocarcinoma." (PMID 30055587, 2018). "In particular, the identification of mutations in the gene encoding epidermal growth factor receptor (EGFR) in NSCLC patients with adenocarcinoma has led to the utilization of small-molecule tyrosine kinase inhibitors, such as gefitinib or afatinib specifically for that subtype of patients." (PMID 28154808, 2017). "Among NSCLC patients, 32.8% had an EGFR mutation and 88.6% presented adenocarcinoma histology." (PMID 29254220, 2017). "However, the prognostic implication of CT radiomic features in a homogeneous set of patients with adenocarcinoma and EGFR-sensitizing mutations has yet to be described." (PMID 29099855, 2017). "In our study, 11/47 non-adenocarcinoma patients with BMs (23.4%) had EGFR mutations." (PMID 29050314, 2017). "In addition, to patients with adenocarcinoma, the mutation status of the epidermal growth factor receptor (EGFR) plays an important role in guiding the EGFR-based targeted therapy." (PMID 28877268, 2017). "Approximately, 40% of patients diagnosed with NSCLC will develop brain metastasis (BM) during the course of their disease and this risk may be even higher in those with adenocarcinoma with epidermal growth factor receptor (EGFR) mutation." (PMID 29340055, 2017). "Thus, we presented the biologically prognostic values of EGFR mutations and histological classification in patients with adenocarcinoma." (PMID 29065153, 2017). "Because several studies have demonstrated that female patients and adenocarcinoma patients have a higher frequency of EGFR mutations, EGFR status may be a valuable factor to predict survival, rather than gender or histological type." (PMID 28079142, 2017). "The identification of EGFR mutations has paved the way to the discovery of additional targetable oncogenes with a growing list of emerging molecularly defined subtypes, which approximately 60% of adenocarcinomas having a known activating mutation." (PMID 28060728, 2017). "Approximately 60% of the tumors were adenocarcinoma, and 30% were the type of squamous cell, and there was 21 (17.5%) of 120 patients with some mutations for adenocarcinoma, which included 17 (14.2%) with EGFR mutations, and 4 (3.3%) with EML4-ALK rearrangements (detailed data were not presented)." (PMID 28602126, 2017). "Furthermore, Co-SM in EGFR gene, especially both sensitive and resistant mutations, such as L858R + T790M or Exon19 deletion + T790M, was common in Co-SM+ adenocarcinoma." (PMID 28978153, 2017). "What is more, PIK3CA mutation, ERBB2 amplification, HGF overexpression, AXL activation, epithelial-mesenchymal transition, and pathology type transformation, especially adenocarcinoma transformation into small cell lung cancer, have also been reported as causes of secondary resistance to EGFR-TKIs." (PMID 28915624, 2017). "EGFR was mutated in 46.9% of adenocarcinoma cases, which could instruct the clinical application of EGFR TKI instantly." (PMID 28373672, 2017). "Of the 83 patients with adenocarcinoma, 16 underwent additional EGFR mutation detection." (PMID 28877268, 2017). "Therefore, EGFR (epidermal growth factor receptor) mutations account for up to 15% of adenocarcinoma and primarily occurred in the tyrosine kinase (TK) domain of the gene." (PMID 28146051, 2017). "In a subset analysis of Chinese patients participating in the PIONEER study, a prospective molecular epidemiology study of EGFR gene mutations in Asian patients newly diagnosed with advanced NSCLC of adenocarcinoma histology, 50.2% (95% CI: 46.6–53.8%) of patients were EGFR mutation positive." (PMID 28673332, 2017).
adenocarcinoma (continued). "In contrast, EGFR mutations were detected in 21.9% (23/105) of adenocarcinoma samples by the NGS-based ctDNA assay in this study, which is a much higher proportion than detected by direct DNA sequencing yet a lower proportion than identified by Scorpions ARMS-PCR in the previous study." (PMID 29097733, 2017). "Patients with advanced NSCLC, particularly those with adenocarcinomas, are currently tested for the presence of epidermal growth factor receptor (EGFR) mutations, ALK aberrations, and ROS1 aberrations in their tumors because these molecular alterations have therapeutic consequences." (PMID 28367252, 2017). "In addition, the epidermal growth factor receptor mutation rate was higher in the adenocarcinoma histologic type (p<0.001)." (PMID 28832323, 2017). "In addition, in Asian patients with adenocarcinoma histology, an EGFR mutation is found to be present at twice the rate of other populations, reflecting the underlying genetic differences." (PMID 28036300, 2017). "Of 154 adenocarcinoma, EGFR mutation rate is 37.7% (58/154)." (PMID 29290981, 2017). "We found the rate of EGFR mutation to be 20.3% in adenocarcinomas and 7.4% in NSCLC-NOS." (PMID 28832323, 2017). "Adenocarcinomas with EGFR mutations is prevalent among Asians." (PMID 28938635, 2017). "However, an adenocarcinoma cell line with an EGFR L858R + T790M mutation is unaffected by Quinalizarin." (PMID 28134850, 2017). "The mutation rate of EGFR was higher in females than that in males (39.5% vs 29.4%, P=0.076), significantly increased in adenocarcinomas (38.7%) compared to that in the other forms of NSCLC (P < 0.01), but still lower than that reported in some Asian studies of advanced adenocarcinoma (-50%)." (PMID 28935015, 2017). "Additionally, small sample size precluded the ability to identify factors associated with EGFR testing and receipt of erlotinib among patients with earlier stage tumors and non-adenocarcinomas." (PMID 27294665, 2016). "However, both EGFR and K-ras mutations can still exist simultaneously in multifocal adenocarcinomas of lung." (PMID 27070580, 2016). "By multivariate analysis, Cyfra21-1 (HR = 1.543, P = 0.032 for DFS; HR = 2.527, P < 0.001 for OS) and clinical stage (HR = 1.825, P = 0.004 for DFS; HR = 1.694, P = 0.040 for OS) were independent predictive and prognostic factors in all EGFR-mutated adenocarcinoma patients." (PMID 27072585, 2016). "However, there are still a few cases of adenocarcinoma of lung showing discordance for the status of EGFR mutation." (PMID 27070580, 2016). "EGFR mutations were more frequent in adenocarcinoma (P < 0.001)." (PMID 27472739, 2016). "However, we were unable to found a difference in the CEA or Cyfra21-1 levels between EGFR-mutated or wild-type adenocarcinoma patients." (PMID 27072585, 2016). "Thirty (50 %) patients had EGFR mutation and 57 patients had adenocarcinoma subtype." (PMID 26979333, 2016). "In another study, Twist was selectively associated with EGFR-mutated adenocarcinomas." (PMID 27018053, 2016). "However, some of the adenocarcinomas show a discordant status of EGFR mutations between the primary and metastatic sites." (PMID 27070580, 2016). "EGFR-mutation was associated with improved survival, albeit only among stage IV adenocarcinomas." (PMID 27294665, 2016). "Therefore, many studies have focused on patients with the presence of active EGFR mutations, especially those with adenocarcinoma histology." (PMID 25886585, 2015). "With that in view, we examined the correlations between MET gene status as assessed by fluorescence in situ hybridization (FISH) with overall survival (OS) and progression-free survival (PFS) in adenocarcinoma patients with EGFR gene mutations who had received gefitinib therapy." (PMID 25886066, 2015).
adenocarcinoma (continued). "The high frequency of EGFR mutation in P-LC may be caused by following: most cases were adenocarcinoma with lepidic and acinar growth pattern; the majority of patients were female; there was a high ratio of nonsmoker; and patients were Asian." (PMID 25715252, 2015). "In addition, our epidemiological results are in line with literature: KRAS mutations are strongly correlated with smoking habit and adenocarcinoma histology and are mutually exclusive with EGFR mutations." (PMID 26416458, 2015). "EGFR mutations distributed amongst different Adenocarcinoma groups." (PMID 26208325, 2015). "Similarly, Asian patients with adenocarcinoma also have a higher incidence of the EGFR gene mutation than Caucasian patients." (PMID 25886585, 2015). "Among 32 patients with adenocarcinoma, 11 patients had activating mutations in the tyrosine kinase domain of the epidermal growth factor receptor (EGFR), while 10 patiens were wild-type and 11 patients had unknown status." (PMID 26720170, 2015). "The homogeneous distribution of EGFR mutations in all adenocarcinoma patterns of growth supports the hypothesis that they are an early genetic event, often associated to lepidic component." (PMID 26422230, 2015). "Furthermore, EGFR mutations in the adenocarcinoma subgroup were correlated with ERCC1 expression levels (P=0.001)." (PMID 25667646, 2015). "If further research finds it to be similar to the EGFR gene mutation found in adenocarcinoma among high-risk groups, oncologists should consider testing female and non/mild smoking SQCLC patients for EGFR gene mutation status and begin TKIs treatment if appropriate." (PMID 25886585, 2015). "Activating mutations in the EGFR gene accounts for up to 20% of adenocarcinomas." (PMID 26371045, 2015). "Similarly, adenocarcinoma, distant metastasis and chemotherapy exhibited an increase in EGFR mutation risk (by 2.571, 2.810 and 0.367 times, respectively)." (PMID 25013503, 2014). "Furthermore, unconditional logistic regression analysis was used and revealed that female gender, adenocarcinoma, distant metastasis and chemotherapy are also factors associated with EGFR gene mutations." (PMID 25013503, 2014). "Nevertheless, this result suggested that MPEs could be more representative specimens in adenocarcinoma patients with pleural metastasis for the EGFR mutation test." (PMID 24587142, 2014). "Similarly, adenocarcinoma, distant metastasis and chemotherapy showed an increase in EGFR mutation risk by 2.571, 2.810 and 0.367 times, respectively." (PMID 25013503, 2014). "Regarding association between treatment response and clinicopathologic factor, female gender (P = 0.007), adenocarcinoma histology (P = 0.004) and an EGFR mutation status (P = 0.005) were significantly associated with disease control rate achieved by gefitinib treatment." (PMID 25410981, 2014). "The frequency of EGFR mutation has proven to be more common in adenocarcinoma." (PMID 24885205, 2014). "Following identification, specific therapies could then be used, such as the EGFR inhibitors Erlotinib and Gefitinib that showed the greatest benefit in EGFR mutation-positive tumors, which were predominantly adenocarcinoma." (PMID 25003505, 2014). "EGFR mutations are present in 13-15% of Western adenocarcinoma patients." (PMID 25594059, 2014). "We then wondered whether expression of hamartin, p-mTOR or p-TSC2 was associated with EGFR-mutations since approximately 20% of adenocarcinoma of the lung patients’ specimens reveal EGFR-mutations." (PMID 24593867, 2014). "We retrospectively analysed the medical records of 629 patients with adenocarcinoma in Slovenia who were tested for EGFR mutations in order to analyse the cumulative incidence of BM, the time from the diagnosis to the development of BM (TDBM), the time from BM to death (TTD) and the median survival." (PMID 24991207, 2014).
adenocarcinoma (continued). "This study aimed to investigate the utility of the new histological classification for identifying the prognostic subtypes of adenocarcinomas in stage IB patients.Correlations between the classification and the presence of epidermal growth factor receptor (EGFR) mutation status was also studied." (PMID 24885205, 2014). "Furthermore, activating EGFR mutations are very frequent in NSCLC adenocarcinomas and are the target of modern therapy with EGFR inhibitors." (PMID 24456610, 2014). "Similarly, adenocarcinoma, distant metastasis and chemotherapy were found to exhibit an increased risk of EGFR mutation by 2.571, 2.810 and 0.367 times, respectively." (PMID 25013503, 2014). "Furthermore, almost all mutations detected in adenocarcinoma tissue, were in the tyrosine kinase domains of 19 and 21 of exon, which usually account for ~90% of EGFR mutations." (PMID 25013503, 2014). "Moreover, the response to the EGFR-tyrosine kinase inhibitors, gefitinib and erlotinib, is strongly associated with the adenocarcinoma subtype." (PMID 25120650, 2014). "NCI-H1975 adenocarcinoma cells, which harbor both the L858R substitution associated with sensitivity to Gefitinib and the “gatekeeper” T790M missense mutation linked with resistance to EGFR-TKIs, are refractory to Gefitinib (IC50> 20 μM)." (PMID 25375092, 2014). "In addition, the EGFR gene mutation rate in adenocarcinoma was found to be significantly higher than that in squamous cell and large cell carcinoma (χ2=12.454; P=0.002)." (PMID 25013503, 2014). "Moreover, our results suggest that the overall genomic and transcriptional landscape of adenocarcinoma is only to a minor extent affected by the mutational status of EGFR and KRAS." (PMID 24205279, 2013). "Taking into consideration that in most cases of inoperable NSCLC the existing cytological material is critical, we evaluated the real-time PCR detection of EGFR mutations in exons 18, 19, 20 and 21 of adenocarcinoma cells obtained via FNA, EBUS, TBNA, brushing procedures, and thoracentesis." (PMID 23817662, 2013). "Secondly, EGFR-mutated adenocarcinomas were weakly associated with higher fractions of total LOH compared with KRAS-mutated and EGFRwt/KRASwt tumors both overall and in stage I disease (p=0.05, ANOVA), but not in tumors of higher stages (≥II), or tumors stratified by gender." (PMID 24205279, 2013). "However, supportive of results from the supervised analyses we found that EGFR-mutated adenocarcinomas in general appeared to display a more distinctive expression pattern with enrichment of EGFR-mutated tumors (~60% of all mutations) in specific clusters." (PMID 24205279, 2013). "Previous studies revealed that EGFR mutations were uncommon in non-adenocarcinomas." (PMID 23590575, 2013). "We found hMLH1 expression and adenocarcinoma were independent factors related to EGFR mutations." (PMID 24205245, 2013). "Although several clinical characteristics such as sex, histology, smoking status, the amount of smoking were associated with EGFR mutation status in the univariate analysis, only adenocarcinoma was found to be an independent predictor for EGFR mutations (Odds ratio = 5.4, 95% CI: 2.1–14.0)." (PMID 23724098, 2013). "Interestingly, in NSCLC patients, EGFR-activating mutations are found mostly in those with adenocarcinomas." (PMID 23637683, 2013). "In the subpopulation of adenocarcinomas the rate of EGFR mutations was 40.8%." (PMID 24205040, 2013). "EGFR mutations occurred most often in TTF-1 positive adenocarcinoma." (PMID 23922984, 2013). "EGFR mutations were detected in 71/778 (9.1 %) tested patients; in 66/620 (10.6 %) adenocarcinomas." (PMID 22528563, 2012). "Importantly, the L858R mutation in EGFR is frequently found in human adenocarcinoma and is known to confer ligand-independent EGF signaling." (PMID 23285300, 2012).
adenocarcinoma (continued). "In addition to protein overexpression, EGFR is commonly somatically mutated in close to 40% of adenocarcinomas and 30% of adenosquamous NSCLC (mutations occurring ~50% of nonsmokers and 5–15% smokers)." (PMID 22928112, 2012). "More interestingly, we found that in the subgroup of patients with adenocarcinoma and EGFR mutation, the ones with methylated SFRP5 had a significantly shorter PFS (2.0 months), as compared to the ones with unmethylated SFRP5 (9.0 months) (P = 0.013, Logrank Test)." (PMID 23009178, 2012). "The majority of our patients (40 of 43) presented with adenocarcinoma and 70% had EGFR mutations." (PMID 23110940, 2012). "In adenocarcinomas, we found EGFR mutations in 11 % of cases." (PMID 22528563, 2012). "The EGFR mutations were detected in 12 out of the 36 adenocarcinoma specimens." (PMID 18283321, 2008). "Two recent transgenic mouse models, in which the overexpression of EGFR mutations was targeted in type II pneumocytes, demonstrated that these mutations led to the development of adenocarcinomas and that the tumors responded both to suppression of the EGFR driving signal and EGFR TKIs." (PMID 17973572, 2007). "Although we expected a high frequency of detection of EGFR mutations in this study because of the high proportion of adenocarcinomas (92.3%), we detected EGFR mutations in only 28.2% of the patients enrolled, a lower frequency than in two previous reports on Japanese NSCLC patients." (PMID 17060940, 2006). "It is well known that EGFR mutations are frequently observed in adenocarcinomas." (PMID 17060940, 2006). "As EGFR mutations were observed exclusively in adenocarcinoma patients, we investigated the relationship between the clinical features and other genetic alterations in these adenocarcinoma patients (n=108) and their mutations." (PMID 16052218, 2005). "Hence, the true incidence of K-ras mutations in NSCLC (including non-adenocarcinoma) and their refractoriness to EGFR inhibitors need to be established in further studies." (PMID 15696203, 2005). "Epidermal growth factor receptor mutations may play a key role in the development of smoking-independent adenocarcinoma." (PMID 16052218, 2005). "Thus, including BAC component and well-to-moderate differentiation grade seem histological features of adenocarcinomas with EGFR mutations." (PMID 16052218, 2005). "SCLC may arise from transformation of NSCLC, especially EGFR-mutated adenocarcinoma." (PMID 41373665, 2025). "In the setting of the biopsy-proven histology of primary NSCLC, patients with adenocarcinoma and/or known high-risk oncogenic driver mutations (EGFR, ALK), as well as patients of young age, might be considered to undergo BI due to the higher incidence of BM in this population." (PMID 39941379, 2025). "Furthermore, investigations have shown the presence of EGFR mutations in healthy fine bronchial epithelium alongside mutation‐positive adenocarcinomas, indicating that, in certain cases, EGFR mutations may occur early in the development of LUAD." (PMID 38077251, 2023). "The most common NSCLC-associated EGFR mutations are the point mutation replacing leucine with arginine in exon 21 (L858R) and in-frame deletions in exon 19 (19del), which account for ~85% of all EGFR mutations and are associated generally with having adenocarcinoma histology." (PMID 36376325, 2022). "SCLC with EGFR mutations may be attributed to the combined component of adenocarcinoma." (PMID 35806042, 2022). "Furthermore, the difference in CT features between EGFR exon 21- and 19-mutated adenocarcinomas remains unclear, since it has been proven that TKIs show different targeted effects in cases of EGFR exon 21 and -19 mutations." (PMID 33707479, 2021). "Whether IMA exhibited NKX2‐1/TTF‐1 exon 1 expression was further validated using qPCR, revealing that 19 of 20 (95%) cases exhibited higher exon 1 expression relative to that of exon 4/5, compared to EGFR‐mutated adenocarcinoma that was immunohistochemically positive for TTF‐1." (PMID 34014042, 2021).